MGP (matrix Gla protein)
Diseases named in the same sentence as MGP in open-access papers (continued):
Sharing a sentence is not in itself a finding about the gene and the disease.
glioblastoma (7 papers, 2009 to 2024). The most malignant astrocytic tumor (WHO grade IV). "Contradictory results have also been published in glioblastoma, where both the upregulation and downregulation of MGP have been linked to tumor aggressiveness." (PMID 36977707, 2023). "Increased expression of MGP in glioblastoma cells is associated with increased tumor cells migratory properties in vitro and tumor spreading in vivo, whereas MGP-knock down leads to opposite effect." (PMID 30257426, 2018). "On the other hand, up-regulation of MGP transcript in breast tumors and glioblastomas is associated with tumor progression and poor prognosis." (PMID 30257426, 2018). "Specifically, gene expression profiling studies revealed that matrix gla protein (MGP), whose function has traditionally been linked to inhibition of calcification of arteries and cartilage, is overexpressed in glioblastomas and associated with worse outcome." (PMID 19712474, 2009). "The MGP gene is overexpressed in different types of cancer, including ovarian, lung, urogenital, skin, and glioblastomas." (PMID 27556859, 2016). "MGP is a migration-promoting protein for glioblastoma, suggesting that it can promote the cancer spreading." (PMID 25210519, 2014). "In this study we have demonstrated that MGP expression at mRNA and protein levels is upregulated in glioblastoma tissues and cell lines, confirming previous expression profiling studies using DNA microchip analyses." (PMID 19712474, 2009). "The initial finding of increased MGP expression in glioblastoma tissues compared to normal cortex led us to experiments with glioblastoma cell lines with different migratory phenotype." (PMID 19712474, 2009). "In order to analyze the role of MGP in glioblastomas, we performed expression, migration and proliferation studies." (PMID 19712474, 2009). "Real-time PCR and ELISA assays confirmed overexpression of MGP in glioblastoma biopsy specimens and cell lines at mRNA and protein levels as compared to normal brain tissue." (PMID 19712474, 2009). "Matrix gla protein (MGP) is one of the mesenchymal genes overexpressed in glioblastoma samples as well as in recurrent gliomas undergoing malignant progression." (PMID 19712474, 2009). "However, different levels of MGP transcripts were observed in different human and rat glioblastoma cell lines and MGP protein released to culture medium was observed in glioblastoma cell line as well." (PMID 30257426, 2018). "In glioblastoma, MGP promotes tumor growth and angiogenesis." (PMID 27556859, 2016). "MGP is highly expressed in cancers of the ovary, testes, kidney, prostate, and glioblastomas but its function in neoplastic cells is unknown." (PMID 25210519, 2014). "MGP promotes angiogenesis and growth in xenografts of glioblastoma." (PMID 25210519, 2014). "Collectively, these findings suggest that MGP is involved in glioblastoma cell migration in vitro." (PMID 19712474, 2009). "MGP might regulate cell migration via vitronectin receptors of the integrin family, which are known to play important roles in glioblastoma migration and invasion." (PMID 19712474, 2009). "The mechanisms linking MGP knockdown and reduced migration of glioblastoma cells remain to be determined, but based on available evidence it is conceivable that interactions with members of the bone morphogenetic protein (BMP) family and the ECM component vitronectin are involved." (PMID 19712474, 2009). "In addition, MGP effects on glioblastoma cell migration might be mediated by binding of MGP to vitronectin." (PMID 19712474, 2009). "To verify MGP overexpression on protein levels we performed immunohistochemistry using both frozen and paraffin sections, which showed distinct staining for MGP in tumor cells of all glioblastomas examined (n = 10), while cells of normal autopsy brains were negative or only faintly positive." (PMID 19712474, 2009). "Thus, the migratory promoting effect of MGP on glioblastoma cell lines might be mediated by both BMPs and vitronectin." (PMID 19712474, 2009).
glioblastoma (continued). "Two other glioblastoma cell lines, U343MG and H4, showed 11.2-fold and 5.6-fold higher MGP mRNA expression compared to normal brain tissue." (PMID 19712474, 2009). "The amount of MGP mRNA in glioblastoma tissues (n = 10) was 2.6 – 21.4 fold higher compared to normal cortex tissues (n = 3, set as 100%, ± 3.4%)." (PMID 19712474, 2009). "Taking into account previous data on negative prognostic effects of MGP overexpression in glioblastomas, our data suggest that upregulation of MGP in concert with other ECM-related components may result in unfavorable prognosis via increased invasion." (PMID 19712474, 2009).
Hypertension (7 papers, 2013 to 2025). The presence of chronic increased pressure in the systemic arterial system. "A number of studies found correlations between serum MGP and well-known conventional risk factors for CVD such as age, gender, smoking, obesity, hypertension, and hyperlipidemia." (PMID 38542487, 2024). "In patients with CAC, CACS was significantly associated with the HD vintage (R = 0.27, p = 0.02), pack-years of smoking (R = 0.37, p = 0.002), duration of hypertension therapy (R = 0.28, p = 0.03), plasma levels of osteoprotegerin (R = 0.32, p = 0.01) and MGP (R = 0.305, p = 0.03)." (PMID 23317172, 2013). "Our finding of an apparent lack of association between dp-ucMGP and blood pressure might be explained by the expected effect of MGP, and hence dp-ucMGP, on calcification, a pathogenesis following hypertension rather than causing hypertension." (PMID 39567396, 2024). "MGP expression in PBMC was lower in patients with abdominal obesity, arterial hypertension, and hyperlipidemia." (PMID 38542487, 2024). "Chronic infusion of BMP-4 induces endothelial dysfunction and hypertension, and treatment with the BMP antagonist, matrix Gla protein, and BMP inhibitors prevents the development of ATS." (PMID 34103026, 2021).
osteoarthritis (7 papers, 2011 to 2024). A noninflammatory degenerative joint disease occurring chiefly in older persons, characterized by degeneration of the articular cartilage, hypertrophy of bone at the margins and changes in the synovial membrane. "In this study based on spontaneous OA in the DH guinea pig model, we have described associations between MGP expression and the natural history of degenerative joint disease." (PMID 34641845, 2021). "It is notable that Mgp knockout mice displayed inappropriate calcification of cartilages, and that human chondrocytes derived from patient of osteoarthritis produced less carboxylated MGP (cMGP) and more undercarboxylated MGP (ucMGP)." (PMID 31212662, 2019). "Based on this study performed on male Dunkin-Hartley guinea pig spontaneous osteoarthritis model, our findings confirmed that elevated expression of MGP in DH guinea pigs may be concluded link to increased OA severity." (PMID 34641845, 2021). "In clinical studies on osteoarthritis, the γ-carboxylation of matrix Gla protein (MGP) and gla-rich protein (GRP) may have a protective role for the disease." (PMID 31212662, 2019). "Since Gla proteins have a very high affinity to Ca++ and pathologic mineralization is thought to be an important factor in OA, our hypothesis was that “the levels of GRP and MGP in the synovial fluid are expected to be significantly elevated in osteoarthritis”." (PMID 39274372, 2024). "However, we think that the results of our study support the idea that “MGP may play an important role in the molecular mechanism of osteoarthritis”." (PMID 39274372, 2024). "To address this issue, we focused our attention on the expression levels of molecules that were previously shown to be modulated during the onset of IVD degeneration or osteoarthritis (COL1A1, COL2A1, AGC1, BMP2, MMP13, MGP and P21)." (PMID 21726455, 2011).
colorectal cancer (6 papers, 2016 to 2024). A primary or metastatic malignant neoplasm that affects the colon or rectum. "Targeting MGP has demonstrated potential in reducing the growth of colorectal cancer tumors and reversing resistance to certain chemotherapies." (PMID 37777759, 2023). "However, the relation between the biological functions of MGP and the immune response in colorectal cancer (CRC) remains unclear." (PMID 35414780, 2022). "In our previous work, we showed a positive correlation between the expression of RUNX2 mRNA in colorectal cancer (CRC) tissue samples and MGP expression; therefore, we wanted to evaluate if RUNX2 affected MGP transcription regulation." (PMID 39684309, 2024). "Analysis of data from two independent Gene Expression Omnibus (GEO) colorectal cancer (CRC) datasets (GEO: GSE6988 and GSE20842) suggested that MGP was overexpressed in CC and rectal cancer (RC) at the mRNA level." (PMID 32405535, 2020).
COVID-19 (6 papers, 2020 to 2025). A disease caused by infection with severe acute respiratory syndrome coronavirus 2. "The vitamin K metabolism and depletion during COVID-19, together with the decrease in the vitamin K-dependent activation of MGP leaves the elastic fibers in the hepar unprotected against infection, with increased thrombogenicity." (PMID 38542487, 2024). "In a cohort of 138 COVID-19 patients and 138 population controls, we measured plasma dephosphorylated-uncarboxylated Matrix Gla Protein (dp-ucMGP), which reflects the functional vitamin K status in peripheral tissue." (PMID 34207745, 2021). "In summary, all these antimicrobial, anticancer and in silico studies revealed that newly synthesized MGP analogs possess promising antiviral activity, to serve as a therapeutic target for COVID-19." (PMID 34834107, 2021). "MGP is also expressed at high levels in heart, kidney, and lung which is particularly interesting in the context of several comorbidities and collateral effects observed in the COVID-19 patients." (PMID 32974353, 2020).
heart failure (6 papers, 2018 to 2023). Inability of the heart to pump blood at an adequate rate to meet tissue metabolic requirements. "Increased BP, cardiac remodeling, and heart failure, which are associated with arterial stiffening, can upregulate MGP expression." (PMID 37181121, 2023). "Vitamin K is associated with reduced cardiovascular disease risk such as heart failure, possibly by carboxylation of matrix-gla protein (MGP), a potent inhibitor of vascular calcification." (PMID 34666769, 2021). "Our study supports a role of activated MGP in maintaining myocardial integrity and diastolic LV performance and can potentially be translated into new strategies for managing diastolic LV dysfunction and preventing its progression to heart failure." (PMID 29529056, 2018). "Elevated dephosphorylated MGP (dpMGP) has been found in patients with CKD, heart failure, CAVD, aortic stenosis and other CVD events." (PMID 33101359, 2020).
osteosarcoma (6 papers, 2018 to 2025). A usually aggressive malignant bone-forming mesenchymal neoplasm, predominantly affecting adolescents and young adults. "Furthermore, MGP serum level is associated with lung metastasis in osteosarcoma patients." (PMID 30257426, 2018). "Ectopic MGP expression in osteosarcoma cells promotes lung metastasis independently of Glu γ-carboxylation of MGP." (PMID 32322728, 2020). "A precedent to the role for MGP in possible niche function has been documented with regard to osteosarcoma metastasis." (PMID 32322728, 2020). "Overexpression of MGP in osteosarcoma cells leads to statistically significant number and size of lung metastasis in mouse model." (PMID 30257426, 2018). "The increased expression of MGP correlated with increased migration of tumor cells in vivo and increased spreading and metastases formation in mouse model of osteosarcoma." (PMID 30257426, 2018). "Additionally, the role of circulating levels of MGP was described for osteosarcoma patients who revealed a significant increase of this protein at the time of diagnosis and then developed lung metastases." (PMID 30257426, 2018). "Thus, MGP appears to enhance the ectopic homing of osteosarcoma cells in lungs, where, as a secreted bioactive molecule, it may act on lung parenchyma to induce factor(s) for the survival/growth of osteosarcoma cells." (PMID 32322728, 2020). "Recently, MGP has been identified as a metastasis-related poor-prognostic factor for osteosarcoma, and notably, its prometastatic activity is independent of Glu γ-carboxylation, indicating that uncarboxylated MGP is functional in a setting other than ossification." (PMID 32322728, 2020).
endothelial dysfunction (5 papers, 2020 to 2025). In vascular diseases, endothelial dysfunction is a systemic pathological state of the endothelium (the inner lining of blood vessels) and can be broadly defined as an imbalance between vasodilating and vasoconstricting substances produced by (or acting on) the endothelium. "Vitamin D deficiency is highly prevalent in CKD and has been repeatedly associated with endothelial dysfunction and VC, probably by downregulating the expression of MGP." (PMID 32839405, 2020). "Among the polymorphisms of MGP, FMD was significantly reduced in the CT genotype of rs4236 compared to CC and TT genotypes, indicating an endothelial dysfunction and hence risk of CVD (P value = 0.041)." (PMID 39246453, 2024). "We conclude that genetic variants of MGP and NOS3 enhance the risk of CKD and are associated with endothelial dysfunction, which predisposes to CVD." (PMID 39246453, 2024). "CT genotype of MGP (rs4236) and CT genotype of NOS3 (rs2070744) variants were found to be associated with decreased FMD, indicating endothelial dysfunction, the harbinger of CVD." (PMID 39246453, 2024). "The CT genotype of MGP (rs4236) polymorphism and CT genotype of NOS3 (rs2070744) polymorphism were found to be associated with decreased FMD, indicating endothelial dysfunction, the harbinger of CVD." (PMID 39246453, 2024). "Given their possible involvement in key molecular pathways—ranging from oxidative stress and low-grade inflammation to endothelial dysfunction, altered mineral metabolism and tissue remodeling—RBP4, LCN2, ApoM, Klotho and MGP represent more than isolated biomarkers." (PMID 41303567, 2025). "When this complex system does not function adequately, proteins like MGP and Gas6 will function improperly, which may favor vascular calcification and endothelial dysfunction and therefore could affect stroke recovery." (PMID 41155747, 2025). "However, The CT genotype of MGP (rs4236) had decreased FMD, indicating endothelial dysfunction." (PMID 39246453, 2024).
gastric cancer (5 papers, 2016 to 2024). A primary or metastatic malignant neoplasm involving the stomach. "Wang and colleagues indicated that the MGP protein could directly bind to the p-STAT5 in the nucleus and activate JAK2/STAT5 signaling in gastric cancer, further facilitating tumor progression." (PMID 36276992, 2022). "Matrix Gla protein is a novel transcriptional co‐activator of STAT5 by interacting with phospho‐STAT5 in the nuclei, which facilitates STAT5 binding to target gene promoters and subsequently promotes gastric cancer cell proliferation, migration, invasion and survival." (PMID 32086862, 2020). "However, the function of intracellular MGP in gastric cancer (GC) cells remains largely unknown." (PMID 32086862, 2020).
hyperphosphatemia (5 papers, 2014 to 2025). Abnormally high level of phosphate in the blood. "In CKD, hyperphosphatemia and decreased functionality of calcification-regulating proteins such as MGP and fetuin-A contribute to the development of medial calcification." (PMID 39684805, 2024). "Hyperphosphatemia, hypercalcemia, hyperparathyroidism, and other factors induce vascular calcification, while matrix GLA protein, klotho, magnesium, and other factors inhibit progression of vascular calcification." (PMID 29614972, 2018). "During the arterial media calcification process, an imbalance of calcification inhibitors (ie, pyrophosphate [PPi], matrix Gla protein [MGP], and fetuin-A) and stimulators (ie, hyperphosphatemia, hypercalcemia, and uremic toxins) is observed." (PMID 38764790, 2024).
melanoma (5 papers, 2013 to 2023). A malignant, usually aggressive tumor composed of atypical, neoplastic melanocytes. "Further in vitro and in vivo studies are warranted to validate these results at the gene and protein level and to assess the potential diagnostic and prognostic relevance of MGP, CD133, and IGF expression in clinical melanoma specimens." (PMID 23915418, 2013). "Indeed, secreted SPARC by melanoma cells promotes vascular permeability and tumor cells expressing MGP present an increased adhesion ability to the endothelium." (PMID 30546831, 2018). "Furthermore, gene profiling of the CD133+ subset of the D10 melanoma cell line has resulted in the identification of 1 gene, i.e., MGP, consistently upregulated, in comparison with the CD133- subset of the same cell line." (PMID 23915418, 2013). "MGP was negative in colorectal adenocarcinoma, gastric adenocarcinoma, thyroid carcinoma, and melanoma, while mild-to-moderate positivity was found in 31.1% (99/318) of hepatocellular carcinomas." (PMID 36284362, 2022). "Moreover, the melanoma cell lines AN and M14 did not alter the phenotype of the PFs as the expression of the two PF markers CLEC3B and CCRL1 showed little change in the PFs but decreased the RF marker (MGP) expression in the RFs (*** p < 0.001 for both AN and M14)." (PMID 36232952, 2022).
prostatic carcinomas (5 papers, 2009 to 2024). "Similarly, overexpression of MGP was observed in primary renal and prostatic carcinomas, while a loss of MGP expression in metastatic renal cell carcinoma and prostatic carcinoma as compared to the primary tumors was also reported." (PMID 32086862, 2020).
Stroke (5 papers, 2020 to 2025). Sudden impairment of blood flow to a part of the brain due to occlusion or rupture of an artery to the brain. "TT genotype of the MGP SNP rs1800801 is associated with stroke recurrence in the North American Caucasian population." (PMID 39246453, 2024). "Low nutritional intake and bioavailability of vitamin K appears to be a plausible risk factor for stroke, via the importance of vitamin K in the maturation of MGP (one of the vitamin K–dependent proteins) as an inhibitor of tissue calcification." (PMID 35645985, 2022). "In this analysis, we observed an independent association between the AA genotype of the MGP SNP rs1800801 and recurrent stroke within the first year in North American Caucasians." (PMID 32584873, 2020). "We found that the AA genotype of MGP SNP rs1800801 is associated with recurrent stroke within the first year after ischemic stroke in North American Caucasian." (PMID 32584873, 2020). "Thus, additional investigation is required to determine whether genetic differences, including MGP SNP rs1800801, contribute to the risk of recurrent stroke in acute ischemic stroke patients and whether they can improve accuracy when integrated into clinical prediction models." (PMID 32584873, 2020). "Finally, expression levels of MGP were not measured in our study and further studies are needed to determine whether vitamin K is associated with stroke through this pathway." (PMID 35645985, 2022). "The MGP SNP rs1800801 was in Hardy-Weinberg equilibrium in patients with and without first-year recurrent stroke (p = 0.928 and p = 0.424, respectively)." (PMID 32584873, 2020).
aortic stenosis (4 papers, 2015 to 2025). Aortic valve stenosis is a aortic valve disease caused by the incomplete opening of the aortic valve. "Patients with aortic stenosis had higher levels of dp-uc MGP; however, not statistically significant (4488.7 +/− 3244.97 vs. 2995.43 +/− 1791.58 pmol/L)." (PMID 39857632, 2024).